DPP4 (dipeptidyl peptidase 4)
Diseases named in the same sentence as DPP4 in open-access papers (continued):
Sharing a sentence is not in itself a finding about the gene and the disease.
diabetes (continued). "Previous studies in rodents have shown that molecules, including angiotensin II (AngII), dipeptidyl peptidase-4 (DPP4), and semaphorin3E, are suppressed with vaccines targeting these molecules, thus ameliorating the pathogenesis of hypertension or diabetes." (PMID 39160276, 2024). "It is a specific inhibitor of dipeptidyl peptidase-4 (DPP-4) and is used alone or in conjunction with other medications for diabetes." (PMID 39065773, 2024). "Incretin-based therapies, such as glucagon-like peptide-1 receptor agonists (GLP-1RAs) and dipeptidyl peptidase-4 (DPP-4) inhibitors, have become crucial in the treatment of type 2 diabetes mellitus." (PMID 38440177, 2024). "Future studies should aim to clarify the role of DPP-4 inhibitors in selected DM1 patients with concomitant diabetes." (PMID 39274465, 2024). "GLP-1 receptor (GLP-1R) agonists and DPP-4 inhibitors are two examples of novel diabetes medications that work to enhance the function of incretins because of their critical role in glycemia regulation." (PMID 38337597, 2024). "In summary, we demonstrate the potential protective effects of IL-10-modulated adipose-derived stromal cells in decreasing diabetes-induced DPP4 activity, insulin resistance, and liver gluconeogenesis." (PMID 39125659, 2024). "In a landscape of complex comorbidities and evolving therapeutic options, DPP-4 inhibitors remain a valuable tool, contributing to the diverse armamentarium needed to manage diabetes in heart failure patients." (PMID 39768866, 2024). "DPP4 activity is correlated with the severity of obesity and diabetes, and plasma DPP4 activity is elevated in patients with T2DM and obesity." (PMID 39125659, 2024). "The most common concomitant medications for diabetes were dipeptidyl peptidase-4 (DPP-4) inhibitors (in 17 participants, 57%) and metformin (20, 67%)." (PMID 38826603, 2024). "The potential of natural sources as DPP-4 inhibitors for the development of novel compounds with therapeutic promise against diabetes have been extensively reviewed recently." (PMID 38675143, 2024). "Dipeptidyl peptidase-4 inhibitors provide potent antidiabetic effects in patients with type 2 diabetes mellitus (T2DM), but their role in the presence of nonalcoholic fatty liver disease (NAFLD) is not well-known." (PMID 39582742, 2024). "DPP-4 inhibitors are an important class of medications for managing diabetes in patients with renal impairment." (PMID 39768866, 2024). "Future research will continue to clarify the role of DPP-4 inhibitors in managing heart failure in diabetes, particularly as we gain insight into molecular mechanisms and long-term safety in special populations." (PMID 39768866, 2024). "This can occur considering bacterial DPP-4 in the bloodstream breaks down incretins, aggravating type 2 diabetes mellitus." (PMID 38337597, 2024). "In our previous report, we demonstrated the beneficial impact of Exendin-4, GLP-1 analog, on DPN in diabetic mice, complementing the existing literature that has shown that DPP-4 inhibitors mitigate the progression of DPN in rodent models of diabetes." (PMID 39201570, 2024). "DPP-4 inhibitors are generally weight-neutral, making them attractive for patients with diabetes who are overweight or obese." (PMID 39768866, 2024). "Dipeptidyl peptidase-4 (DPP4) enzyme inhibition is a therapeutic modality for type 2 diabetes mellitus (T2DM)." (PMID 39507187, 2024). "The diabetes dipeptidyl peptidase inhibitors that target DPP4, included alogliptin, sitagliptin, and linagliptin." (PMID 39713369, 2024). "The DPP4 inhibitor (gliptin) has become an innovative oral therapeutic agent for the treatment of type 2 diabetes mellitus (T2DM)." (PMID 38424257, 2024). "The proposed lead candidates, Tigogenin and Diosgenin unveiled from the SBDD study hold promise for the development of novel inhibitors targeting the DPP4 protein to combat diabetes." (PMID 38551991, 2024).
diabetes (continued). "DPP-4 inhibitors have traditionally been used as a treatment for diabetes through the inhibition of the enzyme DPP-4, which breaks down incretins, a hormone that suppresses glucagon levels and promotes insulin production, thus regulating blood glucose levels." (PMID 39596529, 2024). "In individuals with diabetes, the most frequently prescribed class of anti-diabetic drug was DPP-4 inhibitors, the second-most frequently prescribed drug was SU or glinides, and the third-most frequently prescribed drug was insulin." (PMID 38592103, 2024). "Another strategy in the treatment of diabetics is the inhibition of dipeptidyl peptidase-4 (DPP4), which functions as a negative regulator of the incretin hormone glucagon-like peptide-1 (GLP-1) by cleaving a terminal dipeptide from the hormone." (PMID 38482058, 2024). "Acacetin also exhibits a protective effect on diabetes-induced endothelial cell injury, cardiomyopathy, and kidney disease by targeting PPARα, the Sirt1/Sirt3 signaling pathway, and dipeptidyl peptidase-4 (DPP4)." (PMID 39459239, 2024). "SGLT-2 inhibitors can be used in pasireotide-treated patients with CD or acromegaly with worsening hyperglycemia or newly diagnosed diabetes, with metformin as monotherapy or in combination with DPP-4 inhibitors or GLP-1 RAs." (PMID 39735646, 2024). "Further research continues to elucidate the diverse roles of DPP-4 in physiological processes and its potential as a therapeutic target in conditions such as diabetes, inflammation, and cancer." (PMID 38675143, 2024). "During their hospitalization, 43% of patients with diabetes received metformin, 22.7% received a DPP4 inhibitor, 18.8% received a sulfonylurea, 18.1% received insulin, 1.9% received an SGLT2 inhibitor and 0.1% received a GLP1 receptor agonist." (PMID 39208154, 2024). "The most prevalent diabetes medications received in hospital were metformin (43%), DPP4 inhibitors (22.7%) and sulfonylureas (18.8%)." (PMID 39208154, 2024). "Recent research has reported that elevated levels of DPP4 in elderly diabetes patients possibly induce the reduced mass and function of skeletal muscle." (PMID 37525169, 2023). "In another trial (NCT04371978), scientists used the DPP-4 inhibitor linagliptin at a dose of 5 mg per day on 32 patients suffering with diabetes and COVID-19." (PMID 37064327, 2023). "Sitagliptin is one of many dipeptidyl peptidase-4 (DPP4) inhibitor groups of medications that have been used over many years to control type 2 diabetes mellitus and approved by the FDA in 2006." (PMID 37600820, 2023). "Among them, sodium-glucose cotransporter type 2 (SGLT-2) and DPP-4 inhibitors are promising drugs for reducing the morbidity of CV diseases related to diabetes, as they have positive data published related to CV outcomes." (PMID 37009790, 2023). "As a treatment for type 2 diabetes mellitus, the combined prescription of dipeptidyl peptidase-4 (DPP-4) inhibitors and sodium-glucose cotransporter-2 (SGLT-2) inhibitors is common." (PMID 37111730, 2023). "Another notable finding with respect to drug therapy for diabetes is the low use of GLP1-RA (3.5% combined with DPP4)." (PMID 37175805, 2023). "Next, we considered that pharmacological inhibition of DPP4, which is clinically used to treat diabetes, is also effective at reducing atherosclerotic burden in mice." (PMID 37097759, 2023). "DPP4-mediated comorbidities due to SARS CoV-2 infections among patients with diabetes, hypertension, and cardiovascular diseases are more common." (PMID 37896834, 2023). "Dipeptidyl peptidase (DPP)-4, a therapeutic target for type 2 diabetes mellitus, is also involved in autophagic flux and cancer biology." (PMID 37760498, 2023). "Unlike the effectiveness of GLP-1 agonist studies on NAFLD, most studies showed that a DPP-4 inhibitor led to little improvement in patients with diabetes and NAFLD." (PMID 37374110, 2023).
diabetes (continued). "Dipeptidyl peptidase-4 (DPP-4) inhibitors, commonly referred to as gliptins, constitute a class of medications primarily employed for the management of type 2 diabetes mellitus (T2DM)." (PMID 38002034, 2023). "Soluble DPP-4 (s-DPP4) is well-known in the diabetes literature leading to the development of several inhibitors which help lower blood glucose levels." (PMID 37280551, 2023). "As dipeptidyl peptidase-4 inhibitors are becoming more utilized in the treatment of diabetes, it is important to recognize their side effects and become more familiar with them." (PMID 37090411, 2023). "DPP4 expression is significantly changed in various clinical situations, including cancer, inflammation, obesity, and diabetes." (PMID 37624423, 2023). "Four patients were on diabetes diet only, while 16 had a metformin monotherapy (Hb) or were on a combination with other oral glucose lowering drugs (4 on DPP4-inhibitors and 7 on SGLT2-inhibitors)." (PMID 36771218, 2023). "Several natural products and their extracts targeting potential receptors for diabetes treatment such as dipeptidyl peptidase-IV (DPP-4) and matrix metalloproteinase-9 (MMP-9) for wound healing of DFU have been well studied and reviewed." (PMID 37894660, 2023). "In a 2021 experiment that explored the effects of empagliflozin and gemigliptin (a DPP-4 inhibitor used to treat diabetes) on macrophage inflammatory responses, it was discovered that empagliflozin exhibited anti-inflammatory properties." (PMID 38002034, 2023). "Dipeptidyl peptidase (DPP)-4, a therapeutic target for type 2 diabetes mellitus, is also involved in autophagic flux." (PMID 37760498, 2023). "The most common treatment patterns of type 2 diabetes mellitus included the use of metformin monotherapy (20.5%), followed by the combination of metformin + dipeptidyl peptidase-4 inhibitor (13.4%)." (PMID 37403118, 2023). "In a recent study, DPP-4 inhibitors are suggested for hospitalized COVID-19 patients suffering from diabetes, but the use of sulfonylureas and metformin against SARS-CoV-2-infected diabetic patients is still controversial." (PMID 36839456, 2023). "Regarding the drugs, the most commonly used drug for diabetes mellitus was thiazolidine in 42.9% (15/35), followed by dipeptidyl peptidase-4 inhibitor (DPP4i) and metformin in 34.3% (12/35) of the patients with diabetes." (PMID 37130431, 2023). "This article sheds light on the various scaffolds that can be used in the designing and development of novel synthetic compounds to create DPP-4 inhibitors for the treatment of type 2 diabetes mellitus (T2DM)." (PMID 37570832, 2023). "DPP-4 inhibition is an interesting line of therapy for treating Type 2 Diabetes Mellitus (T2DM) and is based on promoting the incretin effect." (PMID 37287751, 2023). "The utilization of Metformin, Sulphonylureas, and DPP-4 inhibitors has witnessed a notable rise in their application for the management of diabetes." (PMID 38155289, 2023). "Clinical trials supporting the role of DPP-4 and its inhibitors in combatting COVID-19 patients with diabetes." (PMID 37064327, 2023). "In STZ-induced diabetic Wistar rats, myricetin decreases DPP-4 activity, its expression, and diabetes-induced NLRP3 inflammasome activation, increasing circulating GLP-1 and insulin levels." (PMID 37305094, 2023). "The most common treatment patterns of type 2 diabetes mellitus included the use of metformin monotherapy, followed by the combination of metformin + DPP4 inhibitor or metformin + DPP4 inhibitor + insulin, and the use of a DPP4 inhibitor + insulin." (PMID 37403118, 2023). "The concept of inhibiting the DPP-4 enzyme as a strategy for treating type 2 diabetes mellitus (T2DM) was introduced around 1998." (PMID 38002034, 2023).
diabetes (continued). "We conducted a prospective observational study to examine immune cell distribution, with a focus on regulatory T cells, following the administration of gemigliptin, a DPP-4 inhibitor, in patients with type 2 diabetes mellitus (T2DM) and chronic kidney disease." (PMID 38065905, 2023). "An earlier study reported that circulating levels of creatinine and BUN were reduced in DPP-4 mutant rats, suggesting that DPP-4 inhibitors protect against kidney injury, especially in individuals with type 2 diabetes mellitus." (PMID 37047505, 2023). "Dipeptidyl peptidase-4 (DPP-4) inhibitors are glucose-lowering drugs for type 2 diabetes mellitus (T2DM)." (PMID 37009790, 2023). "For diabetes treatment, patients chronically received metformin (97%), sulfonylurea (49%), DPP-4 inhibitors (10%), SGLT2 inhibitors (20%) and insulin (24%)." (PMID 37764998, 2023). "The concomitant use of insulin and a DPP-4 inhibitor was recommended by a joint position statement of the American Diabetes Association (ADA) and the European Association for the Study of Diabetes (EASD) in the therapeutic algorithm for T2DM management." (PMID 38021574, 2023). "The aberrant expression of DPP4 is significantly related to the occurrence of obesity, diabetes, cancer, and other diseases." (PMID 36769291, 2023). "This study therefore aimed to investigate the renoprotective effects of SGLT-2 inhibitors and DPP-4 inhibitors on Thai patients with type 2 diabetes mellitus." (PMID 37223658, 2023). "Both SGLT-2 inhibitors and DPP-4 inhibitors showed the same trends of eGFR reductions from baseline in Thai patients with type 2 diabetes mellitus." (PMID 37223658, 2023). "One recent study found that 6.28% of the world population, corresponding to 462 million individuals globally, are affected by diabetes, putting an especially heavy weight on the use of dipeptidyl peptidase 4 inhibitors (DPP-4) in diabetic patients’ therapy." (PMID 37109703, 2023). "This prospective observational study aimed to investigate the distribution of immune cells (particularly regulatory T cells), following the administration of gemigliptin, a DPP-4 inhibitor, in patients with type 2 diabetes mellitus and chronic kidney disease." (PMID 38065905, 2023). "The oral agents used in the treatment of diabetes include metformin, sulfonylureas, dipeptidyl peptidase-4 (DPP-4) inhibitors, SGLT-2 inhibitors, and glucagon-like peptide-1 (GLP-1) receptor agonists." (PMID 37868469, 2023). "Inhibitors of the exopeptidase dipeptidyl‐peptidase 4 (DPP4) are anti‐diabetes drugs and have been shown to reduce steatosis in MASLD patients, though failing to consistently ameliorate liver inflammation and fibrosis in larger meta‐analyses." (PMID 37962490, 2023). "It is considered that DPP-4 inhibitors prevent diabetes-induced activation of node like receptor family, pyrin domain containing 3 (NLRP3) inflammasome that causes metabolic inflammation and insulin resistance." (PMID 37305094, 2023). "This study focused on the most frequently employed diabetes medication, so dipeptidyl peptidase 4 inhibitors (DPP-4), thiazolidinediones, and sodium glucose co-transporter 2 inhibitors users were not considered." (PMID 36817935, 2023). "Noteworthy here is the higher percentage of patients with cardiac conditions, or cardiac conditions and diabetes, using anti-hyperglycemics, especially DPP4 inhibitors, and to a lower degree SGLT2 inhibitors in the non-severe COVID-19 cohort." (PMID 36145576, 2022). "Conversely, DPP-4 inhibitors for the treatment of diabetes mellitus (DM) were expected to have cardiovascular-protective effects, but large randomized clinical trials (EXAMINE, SAVOR-TIMI 53) reported only protection against cardiovascular events." (PMID 35893426, 2022). "Summarizing, the results of the conducted studies confirmed the neuroprotective effects of newly synthesized adamantane derivatives and dipeptidyl peptidase 4 inhibitors in diabetes mice." (PMID 35468904, 2022).
diabetes (continued). "Gliptins are dipeptidyl peptidase-4 inhibitors (DPI-4) that are used to control blood glucose levels in diabetes mellitus." (PMID 35625906, 2022). "Based on the String database, this paper analyzes the relationship between DPP4 and diabetic protein targets, in order to find a new clue for the management of patients with diabetes with COVID-19." (PMID 34996987, 2022). "With the appearance of new classes of oral diabetes drugs with a lower risk of hypoglycaemia (DPP-4 inhibitors and SGLT-2 inhibitors), the debate about the role of SUs in diabetes management has intensified." (PMID 36261824, 2022). "Dipeptidyl Peptidase 4 inhibitors (DPP4is) are a class of antihyperglycemic medications prescribed to patients with diabetes to manage glycaemic control." (PMID 36456992, 2022). "In this retrospective clinical study the effect of vildagliptin, a DPP4 inhibitor, was investigated on cognitive dysfunction in 60 elderly patients with diabetes with additional diagnosis of mild cognitive impairment (MCI)." (PMID 34880449, 2022). "In patients with diabetes, the majority of antidiabetic drugs were metformin, DPP-4 inhibitors and SGLT2 inhibitors." (PMID 36407528, 2022). "SGLT2 inhibition in rodent studies of neuroprotection in diabetes is significantly more effective than other classes of medications such as dipeptidyl peptidase-4 (DPP4) inhibitors." (PMID 35800082, 2022). "Recently, researchers have been targeting dipeptidyl-peptidase-4 (DPP-4) as a new target in diabetes mellitus." (PMID 35431967, 2022). "To summarize, from our in-silico experiment outcomes, we propose dehydro-p-cymene as the potential lead inhibitor of DPP4 protein, thereby discovering new a phytocompound for the effective management of hyperglycemia and diabetes mellitus." (PMID 36014373, 2022). "In this paper, we screened out the diabetes targets and functional modules closely related to DPP4 through protein interaction network, and analyzed the influence of DPP4 module 1 on the whole protein network and the possible pathway." (PMID 34996987, 2022). "A different study about the impact of different antidiabetic agents on individuals with diabetes and COVID-19 showed that DPP4 inhibitors were highly possible to reduce COVID-19 mortality risk in individuals with diabetes." (PMID 36009573, 2022). "DPP4 inhibitors like sitagliptin have shown beneficial effects and are considered an add-on therapy among COVID-19 patients with diabetes." (PMID 36425575, 2022). "DPP4 is also a recognized therapeutic target for type 2 diabetes mellitus (T2DM) through multiple inhibitors." (PMID 35413090, 2022). "DPP4 inhibitors are a kind of hypoglycemic drugs which have been widely used in patients with diabetes." (PMID 34996987, 2022). "We demonstrated that GLP-1 is an essential molecule for the suppression of diabetes-induced inflammation by DPP4 inhibitors." (PMID 35468904, 2022). "This study compared the renoprotective effects of sodium–glucose cotransporter-2 (SGLT2) inhibitors and dipeptidyl peptidase-4 (DPP-4) inhibitors in patients with type 2 diabetes mellitus (T2DM)." (PMID 36142907, 2022). "A total of 1031 diabetes mellitus targets and 43 targets directly related to DPP4 were obtained by screening." (PMID 34996987, 2022). "Weaknesses include not having measurements of BMI or detailed medication data for the replication cohort, particularly with respect to diabetes medications like DPP4 inhibitors." (PMID 35583495, 2022). "It was proposed that the influence of COVID-19 infection was amplified by DPP4 in patients with diabetes, and through its interaction with INS, leptin, IL-6 and other proteins." (PMID 34996987, 2022). "Dipeptidyl peptidase-4 inhibitors (DPP4is) are a group of antihyperglycemic medications for managing type 2 diabetes mellitus." (PMID 36456992, 2022).